BTK (Bruton tyrosine kinase)
Diseases named in the same sentence as BTK in open-access papers (continued):
Sharing a sentence is not in itself a finding about the gene and the disease.
systemic lupus erythematosus (42 papers, 2012 to 2026). An autoimmune multi-organ disease typically associated with vasculopathy and autoantibody production. "BTK inhibition ameliorates autoimmune arthritis and treatsTLR7/IFN-driven murine lupus, while BTK-deficient XID mice show reduced severity in many inflammatory disease models such as autoimmune encephalomyelitis (EAE), colitis, and acute edema." (PMID 33818636, 2021). "Nevertheless, it is clear that BTK treatment in lupus models is consistently associated with a marked effect on multiple B cell compartments and functions." (PMID 29370834, 2018). "BTK inhibition has shown promise in systemic lupus erythematosus (SLE) and RA, and molecules, such as fenebrutinib and evobrutinib, are currently under clinical investigation." (PMID 40869653, 2025). "In line with ibrutinib, the first generation BTK inhibitor, which blocks plasmablast generation and production of autoantibodies in systemic lupus erythematosus, zanubrutinib reduced AQP4–IgG production in vitro." (PMID 38129902, 2023). "BTK inhibitors serve as a promising new therapeutic target and are currently being tested to treat lupus in animal models." (PMID 33324666, 2020). "As a result, CNS indications such as brain disease in systemic lupus erythematosus (SLE) or multiple sclerosis where both macrophage and B cell biologies are implicated in disease pathogenesis may be alternative options for BTK inhibition." (PMID 30758770, 2019). "We and others have previously demonstrated multiple effects by which BTK inhibition can modulate B cell function in lupus models." (PMID 29370834, 2018). "Although it is possible that some B cell modulatory effects are more important than others, the significant benefit provided by BTK inhibition in lupus animal models is probably a function of multiple additive and/or synergistic effects on this key cell type." (PMID 29370834, 2018). "For example, transgenic mice over expressing BTK specifically in B cells produce antinuclear antibody and develop lupus-like symptoms." (PMID 29884225, 2018). "In vivo, BTK inhibited spontaneous germinal center formation in lupus mice, and decreased splenic B cell numbers (marginal zone, follicular, B1, plasmablasts, and plasma cells), and circulating B cells, antibodies and/or autoantibodies." (PMID 29370834, 2018). "A more challenging and clinically relevant assessment of the potential of BTK inhibition to modulate lupus would be in administration of an inhibitor over a prolonged period of time, in a lupus model with multi-organ involvement." (PMID 29370834, 2018). "A previous report demonstrated the benefits of BTK inhibition in mouse models of TLR7/IFN-driven lupus by affecting both BCR and FcR signaling." (PMID 28950886, 2017). "In this respect, some recent studies have revealed that treatment of lupus mice with inhibitors of Bruton’s tyrosine kinase (BTK) can ameliorate disease." (PMID 28456914, 2017). "Such increased expression of several X chromosome-linked genes has been proposed in lupus, allowing certain immune-related genes such as TLR-7, TASL, CD40 ligand (CD40L), and Bruton’s Tyrosine Kinase (BTK) to be expressed from both X chromosomes in female cells." (PMID 41283475, 2025). "Also, qualified reactions with BTK inhibitors have been reported in heterogeneous rodent models of arthritis and lupus." (PMID 38125430, 2023). "Indeed, deletion of BTK in a mouse model that has features of both pSD and lupus results in attenuated disease." (PMID 39916928, 2023). "The role of BTK and efficacy of BTKi have been studied in murine lupus models." (PMID 36294458, 2022). "In murine models of lupus, BTK expression is increased and facilitates the generation of autoantibodies by promoting plasma cell differentiation from pathogenic B cells; BTKi may block the formation of these antibodies." (PMID 34685540, 2021).
systemic lupus erythematosus (continued). "BTK, which plays a crucial role in B-cell development, has been identified as having multiple roles in the production of autoantibodies and the pathogenesis of lupus." (PMID 33324666, 2020). "Interestingly, Rankin and Hutcheson also found that BTK inhibition in lupus can affect the T cell compartment, and suggested that B cells are required for T cell maintenance." (PMID 29370834, 2018). "We treated mice with BI-BTK-1 and examined the development of spontaneous skin lesions and behavioral abnormalities, to investigate if BTK represents a potential therapeutic target for these classic but often treatment-resistant lupus target organ manifestations." (PMID 29370834, 2018). "Furthermore, when BTK inhibitor was used to treat the lupus mice, it alleviated damage in the kidney, and the production of autoantibody." (PMID 29884225, 2018). "Transgenic mice overexpressing BTK spontaneously formed systemic lupus erythematosus (SLE)-like autoimmune pathology involving multiple organs." (PMID 36183125, 2022). "Therefore, the inhibition of BTK represents an attractive potential therapeutic approach for the treatment of immunological disorders such as RA or systemic lupus erythematosus (SLE), in which B cells and myeloid cells induce or sustain an excessive autoimmune response." (PMID 31907670, 2020). "Other emerging agents, including IL-6,IL-1β, and BTK inhibitors, aim to reduce inflammation-driven CVD, echoingfindings from non-lupus trials like CANTOS." (PMID 41356287, 2025). "It is known that BTK, a TEC kinase family member, contributes to lupus autoimmunity as mice overexpressing BTK spontaneously develop lupus-like autoimmune pathology." (PMID 38997544, 2024). "Dysregulated BCR signaling may be a driver of autoimmunity, as B-cell specific overexpression of Bruton’s tyrosine kinase (BTK) induces a spontaneous autoimmune phenotype resembling systemic lupus erythematosus (SLE) and Sjögren’s syndrome (SS) in mice." (PMID 35563492, 2022). "BTK inhibition by ibrutinib significantly decreased B cell and APC activation and reduced the populations of cDCs, macrophages, neutrophils, and MCs, resulting in dampened humoral and cellular autoimmunity in lupus-prone mice." (PMID 39518015, 2024). "The inhibition of BTK could elevate the type I interferon levels and activate TLR signaling in systemic lupus erythematosus and different experimental models." (PMID 34209188, 2021). "In this study, to determine whether HM71224 could attenuate SLE and LN by suppressing BTK activation, the MRL/lpr and New Zealand Black/White F1 (NZB/W F1) mouse models, which have physiological relevance for human lupus, were used." (PMID 28950886, 2017). "However, the effect of BTK inhibition on other central manifestations of murine (and human) lupus, including cutaneous and neuropsychiatric disease, has not been studied to date." (PMID 29370834, 2018).
Autoimmunity (37 papers, 2013 to 2025). The occurrence of an immune reaction against the organism's own cells or tissues. "Although BTK is essential for normal immune function, its dysregulation has been implicated in oncogenesis and autoimmunity." (PMID 40917692, 2025). "The indirect connection of BTK to the disease-associated CXCL12 pathway can be seen by its connection to PLC-γ 2 where a gain-of-function mutation in PLC-γ 2 leads to SLE-like autoimmunity by altering B cell Ca2+ signaling." (PMID 34803999, 2021). "Aberrant BTK expression levels or lineages could significantly increase the risk for oncogenesis or autoimmunity in treated XLA patients." (PMID 40917692, 2025). "Enhanced BTK activity is implicated in the breach of self-tolerance checkpoints in autoimmunity." (PMID 35008785, 2021). "Finally, BCR and TLR are thought to be key activation pathways in marginal zone lymphoma (MZL), often associated with chronic inflammation in the context of autoimmunity and/or infection, implicating BTK as a potential target." (PMID 29455639, 2018). "Furthermore, we showed that circulating IPF B-cells had elevated BTK expression, which could contribute to a loss of immune tolerance and development of autoimmunity in IPF (graphic summary)." (PMID 31651327, 2019). "Phase II and III clinical trials investigating the efficacy of BTK inhibitors for diverse autoimmune conditions are currently underway." (PMID 38638671, 2024). "Given these crucial functions, BTK is recognized as a key target for therapeutic interventions in autoimmune disorders." (PMID 39280007, 2024). "BCR signaling also activates BTK in cells like mast cells, basophils, monocytes, macrophages, and osteoblasts involved in hematogenesis and autoimmunity." (PMID 36986499, 2023). "BTK regulates the function of B cells in host defense and autoimmunity by participating in the BCR signaling pathway." (PMID 37638060, 2023). "BTK activation plays a significant role in signaling downstream mediators of autoimmunity and inflammation." (PMID 36986499, 2023). "The initial evidence of the protective effect of BTK inhibition against autoimmunity comes from animal studies with observations that BTK inhibition reduced disease symptoms whereas transgenic BTK overexpression induced systemic autoimmunity in mice." (PMID 36294458, 2022). "There is strong evidence for BTK being an important driver of B-cell–T-cell interaction, promoting autoimmunity." (PMID 36294458, 2022). "There are also many genes of relevance to immune function and susceptibility for autoimmunity located on the X chromosome, including those encoding IL2-Rγ, IL13-Rα, CXCR3, CD40 ligand, TLR7 and TLR8, TIMP1 and Bruton’s tyrosine kinase (BTK)." (PMID 36518769, 2022). "The function of the high-expression group of BTK was mainly enriched in immune-related activities, such as autoimmunity, cell adhesion, chemotactic cytokines, and T cell receptors signaling pathway." (PMID 34805160, 2021). "Aberrant BCR signaling, in particular enhanced Bruton’s tyrosine kinase (BTK) activity, is possibly implicated in the breach of self-tolerance in autoimmunity." (PMID 34068035, 2021). "Overexpression of BTK in B cells results in germinal center and plasma cell formation, antinuclear antibody production, and autoimmune disorders." (PMID 35008785, 2021). "It has been shown that autoimmunity is induced in transgenic mice overexpressing human BTK in B cells and that inhibition of BTK is effective in reducing or preventing autoimmunity in various murine autoimmune models." (PMID 34068035, 2021). "Across all doses, even those associated with submaximal BTK inhibition, fenebrutinib resulted in clinical benefit for patients with CSU with type IIb autoimmunity, a population that is more refractory to currently available treatments." (PMID 34750553, 2021).
Autoimmunity (continued). "The effects of Ibrutinib on B cell activation (pBTK), plasma B cell (CD138), and IgG levels in the injured spinal cord are consistent with elevated BTK levels and activation following SCI promoting pathogenic B cell activation and autoimmunity." (PMID 35008785, 2021). "Here, we investigated the therapeutic potential of ibrutinib, a Bruton’s tyrosine kinase (BTK) inhibitor used in B cell malignancies, to alter B cell pathology in SSc in an in vitro model of autoimmunity." (PMID 32228672, 2020). "Based on the crucial role of BTK in B cell function, it has been identified as a potential target for the treatment of autoimmune disorders." (PMID 31130959, 2019). "In particular, over-activation of BTK have been shown to drive autoimmunity by enhancing autoantibody production and class switching, promoting B-T cell cross talk and peripheral B-cell loss of tolerance." (PMID 31293582, 2019). "BTK inhibition is expected to impact mechanisms involving B cell- and non B cell-mediated autoimmunity such as RA and lupus via B cell receptor, Fc receptor, and RANK receptor signaling." (PMID 28265691, 2017). "Over the last few years, significant efforts have been made in order to develop BTK inhibitors to treat B-cell malignancies, and autoimmunity or allergy/hypersensitivity but limited success has been achieved." (PMID 26784025, 2016). "While this model does not allow us to explore the effects on B cells, the published data with BTK inhibitors on B cells, and our in vitro data, suggests that BTK inhibition can also affect B cell autoimmunity." (PMID 27192942, 2016). "Mice overexpressing BTK specifically in their B cells also develop SLE-like autoimmunity that can be alleviated by the BTK inhibitor." (PMID 23967355, 2013). "We have therefore elucidated a critical role for BTK, an important target for autoimmunity, in B cell co-stimulation." (PMID 23967355, 2013). "However, after the challenging safety profiles of first-generation BTK inhibitors, there is likely to be a cautious approach to safety in the use of second-generation BTK inhibitors for MS, along with a range of autoimmune conditions." (PMID 38638671, 2024). "Transferable insights may be obtained regarding safety, efficacy and mechanisms of action, which could be relevant to MS, through understanding the development and trial results of BTK inhibitors in other autoimmune conditions." (PMID 38638671, 2024). "Clinician scientists wanted to understand what is currently known about BTK inhibitors, how they work in the laboratory and how safe they could be for treating autoimmune conditions." (PMID 38638671, 2024). "Summary of BTK inhibitors under clinical trial for autoimmune conditions." (PMID 38638671, 2024). "Besides tuning B cell receptor (BCR) activation, BTK takes part in signaling of toll-like and Fc receptors, modulating the inflammatory response; therefore, its excessive activity has been related to autoimmunity." (PMID 36826039, 2023). "The role of BTK in the pathogenesis of autoimmunity has been studied extensively in animal models." (PMID 36359789, 2022). "In the future treatment landscape, BTK inhibitors may represent an alternative to anti-IgE therapy, with a particular role in patients with type IIb autoimmunity who are more refractory or slower to respond to anti-IgE therapy." (PMID 34750553, 2021). "Several studies have shown that ibrutinib, which is one of the BTK inhibitors under development, binds to BTK with high affinity, leading to the inhibition of B cell receptor signaling and resulting in the reduction of B cell activation involved in autoimmunity." (PMID 31130959, 2019). "BTK inhibitors such as ibrutinib have shown impressive clinical responses in patients with B-cell malignancies, but also hold promise for the treatment of autoimmune disorders." (PMID 31293582, 2019). "Consequently, BTK-overexpressing mice develop autoimmunity involving B cell-induced disruption of T cell homeostasis." (PMID 29455639, 2018).
Autoimmunity (continued). "Thus, the upregulation and activation of BTK following SCI are hypothesized to contribute to pathogenic B cell activation and autoimmunity observed following SCI." (PMID 35008785, 2021). "Because of their ability to produce a deep change in the cytokine asset that is (at least partly) responsible for autoimmunity in CLL, to date BTK-inhibitors stand out as the most suitable choice." (PMID 34065833, 2021). "Bruton Tyrosine Kinase (BTK) has a key role in multiple pathways involved in inflammation and autoimmunity." (PMID 34447768, 2021). "In conclusions, because of their ability to mitigate an immunological dysregulation that is (at least partly) responsible for autoimmunity in CLL, to date BTK-inhibitors stand out as the most suitable choice when treatment of autoimmune cytopenias is required." (PMID 34065833, 2021). "Additionally, small molecule inhibitors targeting B cell activation pathways, such as Bruton’s tyrosine kinase (BTK) inhibitors, are currently under investigation in clinical trials for various autoimmune conditions, offering another avenue for potential IDD treatment." (PMID 40688090, 2025). "However, because of the availability of a large range of well-tolerated BTK inhibitors with clinical efficacy in B cell malignancies, inhibition of BCR signaling as a therapeutic target for autoimmunity is mainly focused on targeting BTK, while PLCγ2 is currently not pursued." (PMID 36359789, 2022). "Furthermore, the reduction of disease activity with 200 mg twice daily fenebrutinib in patients with and without type IIb autoimmunity indicates that BTK is crucial for maintaining pathology in type I and IIb autoimmune CSU." (PMID 34750553, 2021).